MSH3 (mutS homolog 3)
Diseases named in the same sentence as MSH3 in open-access papers (continued):
Sharing a sentence is not in itself a finding about the gene and the disease.
adenoma (8 papers, 2019 to 2024). A neoplasm arising from the epithelium. "This clade represents the molecular alterations required to evolve from a CD-causing ACTH-adenoma to a more aggressive tumor, or even to a CA and is characterized by the gene encoding MSH3 (c.235A > G [rs1650697], p.I79V)." (PMID 35563252, 2022). "In line with the expected mutation type, we identified a significant increase of indels in MSH3-deficient adenomas compared to HGCA, including a substantial number of 4 bp deletions." (PMID 34843512, 2021). "In the MSH3-deficient adenomas, most indels were 3 or 2 bp in size, although a substantial number of indels affecting 4 bp and a few affecting > 4 bp were also detected." (PMID 34843512, 2021). "The proportion of indels in the MSH3-deficient adenomas was significantly (p < 0.0001) higher than in sporadic adenomas (HGCA)." (PMID 34843512, 2021). "A key finding of the present study was that almost all (8/9) of the MSH3-deficient adenomas harboured truncating somatic APC variants as the most relevant driver mutation that is supposed to initiate colorectal tumour formation." (PMID 34843512, 2021). "The proportion of APC indels in the MSH3-deficient adenomas was compared with the fraction of APC indels observed among APC variants (somatic and germline) from other sources." (PMID 34843512, 2021). "Among the most interesting driver genes identified in the present MSH3-deficient adenomas are ACVR2A and ARID2." (PMID 34843512, 2021). "In MSH3-deficient adenomas, the occurrence of APC indels in a repetitive sequence context was significantly higher than in FAP patients (p < 0.01)." (PMID 34843512, 2021). "In the MSH3-deficient adenomas, the majority of the 1–3 bp indels occurred in a repetitive sequence context." (PMID 34843512, 2021). "The predominant variant type in the present MSH3-deficient adenomas (C:G>T:A transitions) is consistent with that reported in WES studies of sporadic and FAP-related colon adenomas." (PMID 34843512, 2021). "Further promising driver genes affected in four different MSH3-deficient adenomas, are the ARID genes." (PMID 34843512, 2021). "The most frequently observed Single Base Substitution (SBS) in the MSH3-deficient adenomas was the C:G>T:A transition." (PMID 34843512, 2021). "Analysis of MSH3-deficient adenomas individually revealed that missense variants were the predominant functional type, followed by silent variants." (PMID 34843512, 2021). "In summary, the present data suggest that compared to sporadic adenomas (HGCA), the somatic mutation spectrum of MSH3-deficient adenomas is characterised by a general increase in the number of indels and a more specific pattern of somatic variants." (PMID 34843512, 2021). "Such an approach could also help determine whether and how variant MSH3 contributes to adenoma formation." (PMID 38243056, 2024). "Also in a recent study, whole exome sequencing in 9 MSH3-related adenomas showed pathogenic somatic APC variants in all but one adenoma." (PMID 35675019, 2023). "However, due to the relatively small number of somatic SBS in the MSH3-deficient adenomas, the possibility of additional signatures in MSH3-related CRC cannot be excluded." (PMID 34843512, 2021). "While variants in established cancer driver genes were identified in several of the present MSH3-deficient adenomas, each of the known more specific drivers of colorectal tumourigenesis (KRAS, FBWX7) was affected in only a single adenoma with the exception of APC." (PMID 34843512, 2021). "Interestingly, the fraction of 1 bp deletions in MSH3-deficient adenomas was considerably lower than that reported in HGCA, suggesting the involvement of differing mutational mechanisms." (PMID 34843512, 2021). "In addition, the fraction of indels among all somatic APC variants (90%) and the fraction of APC indels in repetitive sequences was significantly higher in the MSH3-deficient adenomas." (PMID 34843512, 2021).
adenoma (continued). "In addition, established and published cancer driver genes mutated in at least one MSH3-deficient adenoma were selected." (PMID 34843512, 2021). "In addition, the MSH3-deficient adenomas harboured one to five (recurrent) somatic variants in 13 established or candidate driver genes for early colorectal carcinogenesis, including ACVR2A and ARID genes." (PMID 34843512, 2021). "The amount of somatic variants in the MSH3-deficient adenomas and the pattern of single nucleotide variants (SNVs) was similar to sporadic adenomas, whereas the fraction of small insertions/deletions (indels) (21–42% of all small variants) was significantly higher." (PMID 34843512, 2021). "MSH3-associated CRC seems to follow the classic APC pathway, as patients with adenomas and CRC carrying APC mutations showed MSH3 deficiency, as confirmed in this study." (PMID 37835512, 2023). "In line with the specific function of MSH3 in the mismatch repair (MMR) system, we identified a characteristic APC mutational pattern in MSH3-deficient adenomas, and confirmed further driver genes for colorectal tumourigenesis." (PMID 34843512, 2021). "As we had performed sequencing of APC in the adenomas of another patient with MSH3-related adenomatous polyposis (sister of 1661.2) in a previous study, the eight APC variants found in those adenomas were also considered in these analyses." (PMID 34843512, 2021). "However, combined with the somatic variants in all MSH3-deficient adenomas, none of the affected genes were recurrently mutated, and none were considered promising candidate genes on the basis of known function or published data." (PMID 34843512, 2021).
ovarian carcinoma (6 papers, 2006 to 2025). A malignant neoplasm originating from the surface ovarian epithelium. "There was one patient with ovarian cancer harboring an MSH3 variant in addition to the BRCA2 variant, with the former variant also possibly contributing to the phenotype." (PMID 41465149, 2025). "For example, LOH is a frequent event for BRCA1 in breast and ovarian cancers, for MSH3 in breast, bladder and non-small cell lung cancers, and for PDGFRL in sporadic hepatocellular carcinomas, colorectal and non-small cell lung cancers." (PMID 21108794, 2010). "The common germline mutations in ovarian cancer includes BRCA1, BRCA2, ATM, MSH3 and PALB257." (PMID 33432021, 2021).
prostate carcinoma (6 papers, 2012 to 2025). A carcinoma that arises from epithelial cells of the prostate gland. "Regarding germline CRC predisposition, common MSH3 polymorphisms were significantly associated with CRC and prostate cancer as low-penetrance risk alleles, and recently high-penetrance pathogenic biallelic germline MSH3 variants have also been associated with CRC and colorectal polyposis syndromes." (PMID 33809179, 2021). "These include FARP1 (found in 2 RASGRF2 fusions from cholangiocarcinoma and PDAC) and MSH3 (found in 6 RASGRF2 fusions from colorectal, ovarian, head and neck, pancreatic, and prostate cancers)." (PMID 40615519, 2025).
colorectal tumors (5 papers, 2011 to 2024). "The DNA MMR protein MSH3 is frequently mutated in MSI+ colorectal tumors, thus making it an attractive candidate for T cell-based immunotherapies." (PMID 22110587, 2011).
endometrial cancer (5 papers, 2015 to 2025). Primary or metastatic malignant neoplasm involving the endometrium (mucous membrane that lines the endometrial cavity). "MSH3 mutations have been mainly linked to endometrial cancer, but there are reports of its relationship with inflammatory processes, such as ulcerative colitis and Crohn’s disease, which considerably increase the likelihood of CRC development." (PMID 37835512, 2023).
esophageal cancer (5 papers, 2012 to 2024). A primary or metastatic malignant neoplasm involving the esophagus.
lung carcinoma (5 papers, 2016 to 2024). "The median survival time for lung cancer patients with the MSH3 Ala1045Thr homozygous variant (GG) was higher than for those with the wild-type genotype (AA) (MST = 16.7 vs 8.7, 95% CI 0.32–1.05, Log-rank p = 0.14)." (PMID 39003369, 2024). "For MSH3 Ala1045Thr polymorphism, heterozygous type genotype (GA) in the co-dominant model females has a twofold increased risk of developing lung cancer." (PMID 39003369, 2024). "As far as our knowledge is concerned, this is the first study to evaluate and analyze the role of MSH3 rs26279 polymorphism towards the risk of occurrence of lung cancer in North Indians." (PMID 39003369, 2024). "Another well-known risk factor for lung cancer is tobacco smoking; therefore, to evaluate the synergistic role of smoking and MSH3 & MSH6 polymorphisms towards lung cancer susceptibility, we stratified our data based on smoking status to study the gene-environment interaction." (PMID 39003369, 2024). "It has been proved that polymorphisms of DNA repair genes, such as the polymorphisms of XPA ‐4G>A (rs1800975), ERCC2 862G>A (rs1799793) 12, MSH3 3133G>A (rs26279), and PMS1 639G>A (rs5742938) 13, are associated with the risk of lung cancer." (PMID 27335251, 2016). "This case–control study focuses on whether MSH3 Ala1045Thr (rs26279) and MSH6 (rs3136228) genetic polymorphisms play any role in modulating the risk for lung cancer." (PMID 39003369, 2024). "Data from our study suggest a lack of any significant association between MSH3 Ala1045Thr polymorphism and the risk of developing lung cancer." (PMID 39003369, 2024). "MSH3 and MSH6 polymorphisms are involved in modulating the risk towards lung cancer." (PMID 39003369, 2024). "Additionally, the prognosis of lung cancer patients was evaluated based on the genotypes of MSH3 and MSH6, stratified by histological subtypes." (PMID 39003369, 2024). "So far as our knowledge is concerned, no study has been evaluated in Indian lung cancer patients to evaluate the role of the MSH3 and MSH6 polymorphism towards lung cancer susceptibility and as a prognostic marker." (PMID 39003369, 2024). "Our data suggest that smoking status does not affect MSH3 Ala1045Thr polymorphism and the risk of developing lung cancer." (PMID 39003369, 2024). "The present study investigated the relationship between MSH3 and MSH6 genes in lung cancer patients." (PMID 39003369, 2024). "MSH3 rs26279 and EXO1 rs9350 altered survival of 180 lung cancer and 602 lung cancer patients treated with platinum-based chemotherapy." (PMID 30038702, 2018).
pancreatic cancer (5 papers, 2020 to 2023). "It remains to be determined whether MSH3 copy number alterations, found in 32% of the TCGA colorectal and 27% of the pancreatic cancer cohort, are associated with the EMAST/non-MSI-H phenotype." (PMID 34298744, 2021). "The MSH3 gene promoter is not hypermethylated in colorectal or pancreatic carcinomas (Illumina Methylation450K CpG island probes cg11646734, cg16401290, cg14865507, cg07526021 and cg18200270)." (PMID 34298744, 2021). "The TCGA data indicate that MSH3 mutations, deep deletion or low mRNA expression are not frequent enough to explain the generation of all the observed EMAST in non-MSI-H colorectal or pancreatic carcinomas." (PMID 34298744, 2021). "Except for MSH3, the rest of the germline mutant genes in non-BRCA carriers with TNBC were involved in the HRR pathway, including BLM, PALB2, NBN, RAD51C, and RAD51D, with the mutation rate of 9.26% (5/54), which increased the risk of other cancers, such as PLAB2 for pancreatic cancer." (PMID 33194720, 2020).
colorectal polyposis (3 papers, 2021 to 2025). "Whole exome sequencing was performed on DNA derived from the colorectal polyps of three patients with MSH3-related adenomatous polyposis, who were members of two independent families." (PMID 34843512, 2021). "Characteristics of colorectal polyps from patients with MSH3-related adenomatous polyposis investigated via whole exome sequencing." (PMID 34843512, 2021). "While predisposing variants in genes such as NTHL1, MSH3, POLE, POLD1, DSC2, and PIEZO1 have been associated with colorectal polyposis, they do not fully mimic the classical FAP phenotype." (PMID 41204315, 2025).
Familial adenomatous polyposis (3 papers, 2021 to 2025). Familial adenomatous polyposis (FAP) is characterized by the development of hundreds to thousands of adenomas in the rectum and colon during the second decade of life. "Recently, we identified biallelic pathogenic germline variants in the MMR gene MSH3 as the genetic cause of a novel, recessively inherited subtype of colorectal adenomatous polyposis." (PMID 34843512, 2021). "Recently, we identified two unrelated families with attenuated colorectal adenomatous polyposis, caused by different compound-heterozygous truncating germline variants in the MMR gene MSH3." (PMID 34843512, 2021). "People with polyposis could have a genetic basis with germline mutations in polyposis-related genes, such as the APC gene, resulting in familial adenomatous polyposis (FAP), MUTYH-associated polyposis (MAP), or, rarely, in other genes such as AXIN2, GREM1, NTHL1, POLE, POLD1, or MSH3." (PMID 40095498, 2025).
Friedreich ataxia (3 papers, 2014 to 2023). An inherited condition that affects the nervous system and causes movement problems. "However, while MSH6 has been shown to be important for expansion in Friedreich ataxia (FRDA) induced pluripotent stem cells, in mouse models of other repeat expansion diseases, it is MSH3 that is important." (PMID 25101111, 2014).
glioblastoma (3 papers, 2022 to 2025). The most malignant astrocytic tumor (WHO grade IV). "Germline MSH3 and ERCC4 mutation may induce a secondary osteosarcoma in glioblastoma patients." (PMID 36271359, 2022).
mismatch repair deficiency (3 papers, 2016 to 2024). "The mismatch repair gene MSH3 has become a major focus for therapeutic development, as unlike other mismatch repair genes, nullizygosity for MSH3 does not cause malignancies associated with mismatch repair deficiency." (PMID 38387080, 2024).
non-small cell lung carcinoma (3 papers, 2010 to 2021). A group of at least three distinct histological types of lung cancer, including non-small cell squamous cell carcinoma, adenocarcinoma, and large cell carcinoma. "MSH3-associated EMAST/MSI-L is a potentially valuable predictive biomarker for colorectal and other cancers, e.g., pancreatic and non-small cell lung carcinomas." (PMID 34298744, 2021).
rectal cancer (3 papers, 2011 to 2022). A primary or metastatic malignant neoplasm that affects the rectum. "Additional AA patient studies have illustrated increased frequencies of MSI-L/EMAST markers in rectal cancers most likely due to somatic inactivation of an alternative MMR gene (MSH3)." (PMID 36280820, 2022).
chondrosarcoma (2 papers, 2021 to 2023). A malignant cartilaginous matrix-producing mesenchymal neoplasm arising from the bone and soft tissue. "Supplementary to the HDR and NHEJ pathways, described in the literature for other cancer entities, the MMR pathway with the key players EXO1, MSH3, and PCNA, is also clearly activated in chondrosarcoma cells after proton application." (PMID 34916568, 2021). "In a previous work, we were able to show that, in addition to homologous-directed repair (HDR) and non-homologous end joining (NHEJ), the mismatch-mediated repair (MMR) pathway with the main players EXO1, MSH3, and PCNA were clearly activated in chondrosarcoma cells after proton application." (PMID 36768638, 2023).
CNS cancers (2 papers, 2024 to 2025). "In contrast, loss of MSH3 is substantially less oncogenic, particularly in the context of CNS cancers, and multiple approaches to therapeutic MSH3 lowering are currently under investigation." (PMID 38749429, 2024).
colorectal adenoma (2 papers, 2021 to 2024). An adenoma that arises from the colon or rectum. "In conclusion, this study describes the ninth known patient with biallelic MSH3 germline variants that are pathogenic and associated with colorectal adenomas and carcinoma." (PMID 38243056, 2024). "Here, human colorectal adenomas were used to analyse somatic variants in MSH3-deficient tumours in more detail." (PMID 34843512, 2021). "The spectrum of somatic genetic variation in colorectal adenomas caused by biallelic pathogenic germline variants in the MSH3 gene, was comprehensively analysed to characterise mutational signatures and identify potential driver genes and pathways of MSH3-related tumourigenesis." (PMID 34843512, 2021).
epilepsy (2 papers, 2020 to 2022). A brain disorder characterized by episodes of abnormally increased neuronal discharge resulting in transient episodes of sensory or motor neurological dysfunction, or psychic dysfunction. "Our study nevertheless identifies high-impact variations in the Asb14, Msh3 and Arhgef38 genes, with important functional consequences in the resulting proteins, albeit with no known relationship with any type of epilepsy." (PMID 32168507, 2020). "However, no Msh3 alteration directly related to any type of epilepsy has been published so far." (PMID 32168507, 2020).
hereditary cancer (2 papers, 2023). Malignant neoplasms occurring in families at a rate greater than that expected by chance and caused by germline mutations in a specific gene. "Another mutation on the same site MSH3 A2723C (p.Gln908Pro) is related to Hereditary cancer-predisposing syndrome but is considered uncertain significance." (PMID 38028594, 2023).
melanoma (2 papers, 2020 to 2023). A malignant, usually aggressive tumor composed of atypical, neoplastic melanocytes. "FAN1 was the most common germline mutation gene in our cohort, of which 27 variations were found, followed by the genes EGFR, ERBB2, and MSH3, which were found mutated 20 times in melanomas of our study." (PMID 32083130, 2020).